OVCA2 (OVCA2 serine hydrolase domain containing)
Description:
Exhibits ester hydrolase activity with a strong preference for long-chain alkyl ester substrates and high selectivity against a variety of short, branched, and substituted esters. Is able to hydrolyze ester bonds within a wide range of p-nitrophenyl derivatives (C2-C14) in vitro, with a strong preference toward substrates of >8 carbons.
Tractability: PROTAC: ubiquitination databases record sites on it; its protein half-life has been measured.
Gene: Protein-coding gene on chromosome 17 (2,042,022 to 2,043,425, forward strand). Ensembl gene ENSG00000262664.
Subcellular location (Human Protein Atlas): Nucleoplasm; Cytosol
Gene Ontology:
Molecular function: carboxylesterase activity; hydrolase activity
Biological process: response to retinoic acid
Cellular component: cytoplasm; cytosol; mitochondrion; nucleoplasm; nucleus
Genetic constraint (gnomAD): Loss-of-function variants: 22 observed, 15.56 expected, observed/expected ratio (o/e) 1.41, 90% interval 1 to 1.88. The synonymous counts are far from expectation, so gnomAD's model fits this gene poorly and the ratio says little. Missense variants: 376 observed, 274.96 expected, observed/expected ratio (o/e) 1.37, 90% interval 1.26 to 1.49. Synonymous variants: 201 observed, 128.16 expected, observed/expected ratio (o/e) 1.57, 90% interval 1.4 to 1.76.
Homologues: Orthologues: mouse Ovca2 (83% identical), rabbit OVCA2 (83% identical), rat Ovca2 (66% identical), tropical clawed frog ovca2 (52% identical), zebrafish ovca2 (45% identical), Caenorhabditis elegans C25G4.2 (36% identical), Drosophila melanogaster CG5412 (34% identical).
Diseases named in the same sentence as OVCA2 in open-access papers:
OVCA2 is named in the same sentence as 6 diseases in open-access papers, as found by Europe PMC text mining. Sharing a sentence is not in itself a finding about the gene and the disease. The quoted sentences say what the papers report.
ovarian carcinoma (2 papers, 2016 to 2017). A malignant neoplasm originating from the surface ovarian epithelium. "The ovarian cancer-associated gene 2 protein (OVCA2) at 17p13.3 was repeatedly reported to be associated with ovarian cancer, and we observed five cases carrying the CNA at this gene region." (PMID 29083376, 2016). "Inactivation of the region around rs7208736 has been linked to several malignancies, such as lung, breast, liver, colon, kidney, and brain, with the genes HIC1 (Hypermethylated in cancer 1) and OVCA2 (Ovarian cancer-associated gene 2) being potential tumor suppressors." (PMID 29065852, 2017).
multiple myeloma (1 paper, 2021). "Also, in contrast with del17p being a marker of poor prognosis, our analysis of the FIMM dataset suggested that high expression of OVCA2 is associated with poor prognosis in multiple myeloma, despite low expression of OVCA2 being associated with del17p." (PMID 33531688, 2021). "Further research is required to determine the role of OVCA2 in multiple myeloma." (PMID 33531688, 2021). "High expression of OVCA2, PAFAH1B3, USP4 and SIAE, and low expression of PCED1B, are poor prognostic markers in MM, suggesting a role for these esterases in myeloma biology." (PMID 33531688, 2021).
ovarian tumors (1 paper, 2023). "H1C1 is a tumor suppressor gene and is primarily studied in human cancer research, and OVCA2 has been mostly studied for its expression in breast and ovarian tumors in humans, but there is little evidence of this gene’s role in cattle." (PMID 37628680, 2023).
cancer (5 papers, 2014 to 2023). A tumor composed of atypical neoplastic, often pleomorphic cells that invade other tissues. "Among potentially clinically-relevant but uncharacterized human serine hydrolases is OVCA2, a serine hydrolase that has been linked with a variety of cancer-related processes." (PMID 32182256, 2020). "This group includes two proteins: OVCA2 (associated with cancer in humans) and DHFR (a dihydrofolate reductase from Schizosaccharomyces pombe)." (PMID 31683580, 2019). "OVCA2 is a human metabolic serine hydrolase with links to cancer proliferation and acetaldehyde remediation." (PMID 32182256, 2020). "OVCA2 has been reported in humans as a key tumor suppressor in different types of cancer." (PMID 31683580, 2019).
tumor (3 papers, 2008 to 2019). "LvFSH is similar to the OVCA2 oncogene, a protein present in tumor proliferation processes, and whether that is relevant to crustacean biology, it hints towards lipid mobilization for energy production and to participate in protein-protein interactions." (PMID 31683580, 2019).
OVCA2 also shares sentences with these, for which no sentence is quoted: lung carcinoma (1 paper).